TLR2 (toll like receptor 2)
Diseases named in the same sentence as TLR2 in open-access papers (continued):
Sharing a sentence is not in itself a finding about the gene and the disease.
co-infection (16 papers, 2012 to 2024). "In vitro co-infection of macrophages led to significantly elevated expression of TLR2 and CD80 compared to bacterial mono-infection, whereas CD163 and CD206 were downregulated." (PMID 36365071, 2022). "Meanwhile, single-PDCoV infection and PDCoV/PEDV co-infection up-regulate TLR2 by 5 DPI and 3 DPI, respectively." (PMID 36376395, 2022). "Conversely, GAS infection induced the overexpression of TLR2, which was even amplified following co-infection." (PMID 36365071, 2022). "comprising differential modification of monocyte-driven inflammation in the event of co-infection as well as alterations in TLR2 and TLR4 mRNA expression." (PMID 29234642, 2017). "Chronic morphine and HIV-1 Tat, in the context of systemic S. pneumoniae co-infection, differentially modulated induction of TLR2/4, which consequently facilitated trafficking of TLR2 → CD3 + CCR5+ and TLR4 → Ly6C+(CCR5+/CXCR4+) immune cells into the CNS." (PMID 26087960, 2015). "Further investigation with other viruses known to stimulate TLR2-dependent cytokine production in co-infection experiments with LCMV-WE will answer the specificity of LCMV-WE inhibition as ligand type plays an important role in TLR2 driven responses." (PMID 23202459, 2012). "Similarly, S. pneumoniae co-infection with H. influenzae involves synergistic inflammation, including the upregulation of TLR2 signaling in the lung and middle ear." (PMID 35680890, 2022). "TLR2 also plays a role in transmission of disease, likely with a multitude of other factors-when a TLR2 agonist (Pam3Cys) was administered in a murine model of co-infection, contact transmission was diminished as well as inflammation and bacterial shedding." (PMID 27981251, 2016). "Special attention has been given to TLR2, which has been shown to mediate the extensive tissue damage, lung necrosis and mortality seen after bactericidal treatment of pneumococcal pneumonia in a murine co-infection model." (PMID 27981251, 2016). "Finally, subjects with latent TB and filarial coinfection have been shown to exhibit decreased toll-like receptor 2 (TLR2) and toll-like receptor 9 (TLR9) expression, which was reversed after successful antifilarial chemotherapy." (PMID 25632943, 2015). "Co-infection with certain bacteria that stimulate TLR2 can lead to HIV reactivation." (PMID 22844428, 2012). "TLR2 expression significantly enhanced in TB, slightly increased in HIV but slightly reduced in TB/HIV coinfection compared to apparently health controls (HC)." (PMID 38660059, 2024). "Here, we observed that PDCoV/PEDV co-infection only has a detectable effect on TLR4 modulation by 3 DPI and single-PDCoV induces TLR4 upregulation by 5 DPI, similar to TLR2." (PMID 36376395, 2022). "In the presence of HIV-1 Tat and systemic S. pneumoniae co-infection, chronic morphine treatment resulted in a significant increase in both TLR4 and TLR2 expressions on inflammatory monocyte (Ly6C+) cell population." (PMID 26087960, 2015). "One possible reason for the reduced TLR2 and TLR9 in our participants with TB/HIV coinfection could be that HIV diminishes TLRs expression and functionality." (PMID 38660059, 2024). "TLR2, like TLR4, was enhanced in participants with TB or HIV, but not so among participants with TB/HIV coinfection, pointing to disease-specific factors modulating expression." (PMID 38660059, 2024). "However, the present data showed that TLR2 was not significantly changed in each infection group compared with the control, which suggested that TLR2 may be not a key contributor to the increased virulence by co-infection and this result is consistent with that of a previous study." (PMID 25906258, 2015).
fibrosis (16 papers, 2009 to 2025). the formation of excess fibrous connective tissue in an organ or tissue in a reparative or reactive process. "Upon presentation of distress from pneumonitis with fibrosis in Tlr2,4−/− and C57BL/6J mice, however, the lavage levels of all 8 cytokines exceeded those of unirradiated controls and showed strain dependent increases." (PMID 28912510, 2017). "We showed that TLR2 deficiency resulted in preservation of LV systolic/diastolic function and less LV fibrosis related to lower collagen formation and less cytokine/chemokine production in the TLR2−/− heart." (PMID 28835616, 2017). "Cardiac fibrosis was significantly lower in TLR2−/− mice compared to WT mice at 4 weeks (p = 0.002) and 8 weeks (p = 0.000)." (PMID 28835616, 2017). "Paun and colleagues analyzed the effects of 18Gy (Gray) WTI on the development of pneumonitis or fibrosis in mice deficient for TLR2 (TLR2−/−), TLR4 (TLR4−/−), and TLR2/4 double knockout mice (TLR2−/−/TLR4−/−)." (PMID 28836991, 2017). "Unexpectedly, Leptospira-infected kidneys from all genotypes, including TLR2/4dko mice, presented fibrosis when compared to their naïve counterparts." (PMID 24498450, 2014). "Gene ontology (GO) terms derived from up‐regulated genes in LOY monocytes were associated with macrophage‐mediated tissue damage and cardiac fibrosis with terms such as ‘Toll‐like receptor 2 (TLR2) cascade’ and ‘transforming growth factor (TGF)‐β signalling pathway’." (PMID 40702883, 2025). "Repeated injection of S. epidermidis in wild-type (WT) mice resulted in substantial peritoneal fibrosis, whereas S. epidermidis injection in TLR2-deficient mice did not result in fibrosis development." (PMID 30538643, 2018). "However, in subsequent studies Hartmann and colleagues found that TLR2 deficient mice re-derived and housed in specific pathogen-free (sp-f) conditions were resistant to BDL- and CCl4-induced fibrosis." (PMID 24333183, 2014). "Finally, excessive recruitment and deposition of HSCs at injury sites is a key driver of liver cirrhosis suggesting that SAA1/TLR2 axis may provide a novel target to anti-fibrosis drug development." (PMID 34113824, 2021). "In conclusion, this study provides evidence that TLR2 and TLR5 are present in pulmonary sensory neurons and that TLR2 and TLR5 expression is enhanced in vagal neurons in the bleomycin-induced fibrosis model." (PMID 29518161, 2018). "This study also showed that TLR2 and TLR5 expression in nodose/jugular neurons was significantly increased in the bleomycin-induced fibrosis model group compared to the saline-treated control group." (PMID 29518161, 2018). "In conclusion, TLR2 and TLR5 expression is enhanced, especially in vagal neurons, in the bleomycin-induced fibrosis model group when compared to the saline treated control group." (PMID 29518161, 2018). "The expression of TLR2 and TLR5 was enhanced especially in vagal neurons in the bleomycin-induced fibrosis model group compared to the saline-treated control group." (PMID 29518161, 2018). "TLR2 transcripts were detected in 29.5% (18/61) and 26.9% (21/78) of DiI labeled pulmonary nodose/jugular neurons and DRG neurons in bleomycin-induced fibrosis model, respectively." (PMID 29518161, 2018). "In the bleomycin-induced fibrosis model, 16.6% (1/6) of TRPM8 positive neurons expressed TLR2, 31.5% (6/19) of TRPV1 neurons expressed TLR2, and 12.5% (1/8) of TRPA1 expressed TLR2 in nodose/jugular ganglion." (PMID 29518161, 2018). "An interesting observation was that HA/TLR2 and HA/TLR4 interactions alter sensitivity to lung inflammation and fibrosis upon lung injury." (PMID 28836991, 2017). "In the bleomycin-induced fibrosis model, 23.5% (4/17) of TRPM8 positive neurons expressed TLR2, 18.2% (4/22) of TRPV1 neurons expressed TLR2, and 44.4% (4/9) of TRPA1 neurons expressed TLR2 in the DRG." (PMID 29518161, 2018).
fibrosis (continued). "Interestingly, this study showed an increase in TLR2 and TLR5 expression in pulmonary nodose/jugular neurons and DRG neurons in both the control group and the bleomycin-induced fibrosis group." (PMID 29518161, 2018).
heart failure (16 papers, 2012 to 2025). Inability of the heart to pump blood at an adequate rate to meet tissue metabolic requirements. "Although TLR1 has not been directly linked to cardiovascular disease (CVD), one study demonstrated that TLR2 activates cardiac remodeling in a TLR1-dependent manner in a heart failure mouse model." (PMID 39828779, 2025). "Inflammation in heart failure is activated and maintained by pattern recognition receptors, which include the toll-like receptors (TLRs) TLR-2, TRL-3, and TRL-4." (PMID 38892020, 2024). "We recently reported that dysregulation of lysosomal autophagy is involved in the pathogenesis of cardiomyopathy induced by DOX in a TLR2-dependent manner and that blocking TLR2 activity provides therapeutic benefits in mouse models of heart failure." (PMID 37124193, 2023). "Involvement of the Toll-like receptor 4 (TLR4) in maladaptive cardiac remodeling and heart failure (HF) upon pressure overload has been studied extensively, but less is known about the role of TLR2." (PMID 34769252, 2021). "Previous study demonstrated that the Toll-like receptors are involved in the progression of CHF, whereas TLR2 can promote myocardial inflammation in heart failure." (PMID 34925046, 2021). "This study aimed to explore the protective role of LCZ696 and the potential mechanism of Toll-like receptor 2 (TLR2) in doxorubicin-induced cardiac failure." (PMID 33928085, 2021). "TLR2 is reported to regulate myocardial ischemia, and sTLR2 may involve in the innate immune response in the pathogenesis of heart failure after acute MI." (PMID 31269974, 2019). "Targeting leukocytic TLR2 may provide a novel therapeutic target to prevent cardiac dysfunction and heart failure due to chronic hypertension." (PMID 28835616, 2017). "However, a comprehensive review reveals that the substrain specific phenotype of wild type mice chosen for backcrossing may also influence the extent and pathology of heart failure in Tlr2 knockout mice." (PMID 27109115, 2016). "Therefore, regulating TLR2 signal may provide a new treatment strategy for heart failure." (PMID 34799616, 2021). "The expression or activation of both TLR2 and TLR4 are up-regulated in experimental models with hypertension and clinical patients with heart failure." (PMID 22808256, 2012). "In a study measuring inflammatory biomarkers in patients with heart failure, expression levels of TLR2 increased in patients in both the Dox group without heart failure and the Dox plus heart failure group." (PMID 36498974, 2022). "However, how DOX activates TLR2-related inflammation and whether LCZ696 could attenuate DOX-induced cardiac failure in a TLR2-dependent manner remain unaddressed." (PMID 33928085, 2021). "Therapeutic strategies that block TLR2 but leave TLR4 activity intact, therefore, may provide a novel option to treat heart failure." (PMID 22808256, 2012).
Hypertension (16 papers, 2013 to 2024). The presence of chronic increased pressure in the systemic arterial system. "The studies also suggest that TLR2 may be targeted to alleviate hypertension-associated vascular injury." (PMID 33318302, 2020). "Thus, in the current study, the association of rs1898830 in TLR2 with lipid traits and hypertension (HT) was investigated in 460 individuals from the general Lebanese population." (PMID 32650372, 2020). "Conversely, although there is abundant literature supporting the role of TLR2 in atherogenesis, there are limited data to support the contribution of TLR2 in hypertension." (PMID 35269587, 2022). "Nonetheless, TLR2 has been observed to mediate the dysfunction of several cell types that contribute to the development of hypertension." (PMID 35269587, 2022). "Since rs1898830 is associated with TLR2-mediated cellular activation, we aimed to study its association with CVD risk factors, such as lipid levels and hypertension." (PMID 32650372, 2020). "Surprisingly, the evidence of TLR2 involved in hypertension is limited to inflammation in the renal system, where TLR2-activated NF-κB signaling is significantly correlated with renal ischemia/reperfusion injury." (PMID 28769820, 2017). "In the colon, however, baicalin treatment counteracts hypertension-associated increases in the expression of Tlr2, TNF-α, IL-1β, and IL-23 but not HMGB1 in the SHRs." (PMID 31719823, 2019). "Mechanistically, SDMA bound to HDL reduced endothelial NO availability via Toll-like receptor-2 (TLR-2), leading to impaired endothelial repair, increased proinflammatory activation, and hypertension." (PMID 38002294, 2023). "In addition, the hypomethylation of TLR2, IFN-γ gene, ADD1, AGTR1, and GCK correlated with hypertension, the CES = 2.3%, 95% CI, −2.51–7.07." (PMID 31805646, 2019). "Although we found a significant relationship basedon genotype frequencies, there were no relationshipbetween TLR-2 del -196-174 genotypes and clinicalparameters except hypertension in patients." (PMID 30124003, 2019). "Furthermore, TLR2 deficiency in mice fails to increase arterial blood pressure after administration of HDL from children and adults with chronic kidney dysfunction (HDLCKD), suggesting that TLR2 activation is involved in HDL-mediated endothelial dysfunction and hypertension." (PMID 23880853, 2013).
Listeria monocytogenes infection (16 papers, 2012 to 2024). "In a mouse Listeria monocytogenes infection model, it was observed that TLR2, responsible for the activation of MCs, plays a crucial role in regulating the synthesis of IL-6 and IL-13 during the innate immune response to this bacterium." (PMID 38638437, 2024). "It has been previously observed during Listeria infection that neonatal neutrophils are depleted in a Toll-like receptor 2 (TLR2) manner." (PMID 38809989, 2024). "Already published data suggest long-term protection by trained innate immunity: two intra-peritoneal injections of 1 mg of the Toll-like receptor-2 agonist zymosan at an interval of 4 days protected mice from Listeria monocytogenes infections for 9 weeks." (PMID 37654489, 2023). "PD-1 can also be selectively induced on myeloid DCs by Listeria monocytogenes infection or by Toll-like receptor 2 (TLR2), TLR3, TLR4, or NOD ligation, but it is inhibited by IL-4 and TLR9." (PMID 30841554, 2019). "We explained this broadened action of nanovaccines formulated with DIO-1 by implementing TLR2 signalling in different innate immune cells that elicit listeriosis-protective Th1 immune responses." (PMID 28903312, 2017). "Although we observed less IL-1β production in Tlr2−/− than Clec5a−/− macrophages incubated with L. monocytogenes, Tlr2−/− mice were more resistant than Clec5a−/− mice to Listeria infection." (PMID 28824166, 2017). "It has been shown that Kupffer cell activation and macrophage infiltration in response to Listeria infection is mediated by TLR-2 dependent secretion of Cxcl1 and Ccl2 and that the macrophage infiltration is also stimulated by exogenous Ccl2 and Cxcl1 capabilities." (PMID 36650530, 2023). "Thus, our findings are similar to the results from a previous study demonstrating that systemic TLR2 activation and bone marrow granulocyte depletion in mice exacerbated Listeria monocytogenes infection and led to uncontrolled bacterial propagation." (PMID 34040603, 2021). "Therefore, we demonstrate that mast cell TLR2 plays a crucial role in regulating the synthesis of IL-6 and IL-13 during Listeria monocytogenes infection in MC." (PMID 34194428, 2021). "Since L. monocytogenes-mediated activation of both CLEC5A and TLR2 induces phosphorylation of Syk and p65, we investigated whether CLEC5A and TLR2 collaborate in host defense against systemic Listeriosis." (PMID 28824166, 2017). "It was observed that inhibition of TLR4 (as opposed to TLR2) in Nr1i2-/- mice could decrease TNF-α and IL-6 levels, which is consistent with the result that Pxr-/-Tlr4-/- mice (compared with Pxr-/-Tlr2-/- mice) could effectively protect against Listeria monocytogenes infection." (PMID 36119030, 2022). "Recent studies have shown, that the synergy of TLR2 and CD40 signaling contributes to activation of resting B cells and TLR2 signaling controls an early Listeria monocytogenes infection which involve co-stimulatory molecule CD40." (PMID 24341851, 2013). "However, the role of CCN1 protein and its interaction with TLR2/4 pathways in intestinal epithelial cells was not elucidated after Listeria monocytogenes infection." (PMID 35269881, 2022).
peritonitis (16 papers, 2011 to 2024). Inflammation of the peritoneum (tissue that lines the abdominal wall and covers most of the organs in the abdomen). "In the peritonitis model, pathogenic synergy was primarily eicosanoid-mediated, whereas in our oropharyngeal model, an exaggerated TLR-2-dependent chemokine and neutrophil response was involved in pathogenesis." (PMID 31546600, 2019). "Employing a peritonitis mouse model, we found that the deficiency of the tlr2/tlr4, myd88 and trif results in decreased neutrophil influx to peritoneal cavities of mice, indicative that in addition to MyD88, TRIF contributes to neutrophilia triggered by TLR4 engagement by Natterin." (PMID 35408954, 2022). "miR-302d is expressed at the early time and downregulated in late time of exudate during acute inflammation in murine peritonitis induced via TLR2/zymosan stimuli." (PMID 30949455, 2019). "Both HSPCs and ILCs are locally present in the model of sterile peritonitis induced by i.p injection of the TLR2 agonist, zymosan." (PMID 30233592, 2018). "Given the strong engagement of TLR2 by ΔbgsA, we were interested in the effects of the deletion of bgsA on enterococcal virulence in a mouse peritonitis model." (PMID 26172831, 2015). "In mouse CLP peritonitis models, TLR-2 and TLR-4 expressions were significantly upregulated in hepatic and splenic macrophages, in the lungs and liver as well as in the intestine when compared to sham mice." (PMID 24830455, 2014). "In addition, a previous study demonstrated that TSG-6 attenuates zymosan-induced mouse peritonitis by decreasing TLR2/NF-κB signaling, dependent on the expression of CD44 on macrophages." (PMID 27917949, 2016). "By using MyD88 knockout and TLR2 knockout mice, it was previously shown that MyD88 contributes to the effective clearance of E. faecium during peritonitis at least in part via TLR2/MyD88 signaling pathway and by facilitating neutrophil recruitment to the site of infection in vivo." (PMID 26317438, 2015). "In this respect, the clot model mimics clinical peritonitis where physical damage and deposition of hemoglobin and fibrin form a bed for infection, and endogenous cell-surface or damage-receptor ligands may contribute to the TLR2/4 interaction." (PMID 21966468, 2011). "In the experimental model of zymosan-induced peritonitis, MSCs secreted TSG-6 that interacts with CD44 on macrophages to reduce the Toll-like receptor 2 (TLR2)/NF-κB signal, thereby reducing the secretion of pro-inflammatory mediators." (PMID 33766127, 2021). "TLR2 plays a predominant role in mediating the proinflammatory effects of SES on human cells and soluble TLR2-attenuated inflammation in the SES peritonitis model." (PMID 22619481, 2012). "We speculate that downregulation of Cox-2 through TLR-2/TLR-4 (via MyD88) in the lungs of Lactobacillus rhamnosus GG or Bifidobacterium longum treated mice may play a protective role in attenuating inflammation induced lung injury following systemic sepsis and peritonitis." (PMID 24830455, 2014).